TNF (tumor necrosis factor)
Diseases named in the same sentence as TNF in open-access papers (continued):
Sharing a sentence is not in itself a finding about the gene and the disease.
Obesity (continued). "Chronic low-grade inflammation, present in obesity and promoted by it, causes a decrease in muscle anabolic function, mediated by changes in the production of factors, such as TNF, IL-6, leptin and GH." (PMID 33802940, 2021). "Obesity is a state of chronic inflammation associated with increases in circulating inflammatory cytokines including TNFα and IL-6 in humans." (PMID 33752736, 2021). "Like leptin, IL‐6 and TNF‐α are produced and released from human adipocytes, and their elevated levels have been found to be strongly associated with all measures of obesity in other studies from Europe or the United States." (PMID 33680494, 2021). "Obesity is associated with higher tumor necrosis factor alpha (TNFα) plasma levels and lower adiponectin levels." (PMID 33689083, 2021). "This decrease of TNF-α and IL-6 can reduce the risk of insulin resistance in a population with obesity." (PMID 34948868, 2021). "Obesity is associated with an increase in adipose tissue size and results in the activation of macrophage inflammatory factors including TNFα, IL-6, and MCP-1 (CCL2), which causes insulin resistance." (PMID 34299302, 2021). "Obesity is associated with higher tumor necrosis factor alpha (TNFα) plasma levels and lower adiponectin levels in adults." (PMID 33689083, 2021). "On the other hand, increasing body fat induces obesity, which causes secretion abnormalities of inflammatory cytokines, such as tumor necrosis factor alpha (TNFα) and insulin resistance." (PMID 33810214, 2021). "Upregulated expression of TNF-α plays a significant role in the induction of insulin resistance linked with obesity and T2DM." (PMID 35052401, 2021). "Although the mechanisms underlying the development of sarcopenia obesity remain to be elucidated, chronic inflammation such as that induced by TNF-α and IL-6 signaling is a possible contributor to the development of sarcopenic obesity." (PMID 33399954, 2021). "Tumor necrosis factor-alpha (TNFα) is primarily secreted by a hyperplastic and hypertrophic adipose tissue, typically associated with obesity." (PMID 34576943, 2021). "The role of TNF-α as a major risk factor for type 2 diabetes and insulin resistance has been debated in several studies linking obesity with diabetic disease." (PMID 34829612, 2021). "Insulin resistance underlying type-2 diabetes (T2DM) superimposed on obesity is known to elevate plasma levels of inflammatory markers such as IL-6, TNFα." (PMID 33510184, 2021). "The enrichment of the Deferribacteres and Tenericutes population is a common phenomenon in obesity, which is positively linked with the pro-inflammatory factors IL-6, TNF-α, and IL-17A, causing aggravation of inflammation in obesity." (PMID 33585429, 2021). "Nevertheless, the deletion of TNF-α diminished these effects—indicating the role of TNF-α induced inflammation on colon carcinogenesis associated with high-fat diet-induced obesity." (PMID 33827616, 2021). "As a result, obesity is associated with a low-grade chronic inflammation characterized by an increase in proinflammatory cytokines (IL-6, TNF-α, IL-1α) and a reduction in anti-inflammatory cytokines (IL-4, IL-10, and IL-13)." (PMID 34439950, 2021). "In summary, the available evidence suggests increased circulating IL-6 and TNF-alpha, which are features of obesity associated insulin resistance, likely causally increase risk of CVD." (PMID 34760952, 2021). "The link between insulin resistance and obesity-associated inflammation has been reported in terms of TNF-α, which is a potent and critical multifunctional proinflammatory cytokine." (PMID 34360840, 2021). "Loss of adipocyte functionality, as it occurs in obesity, is accompanied by the secretion of proinflammatory cytokines, as tumor necrosis factor alpha (TNF-α) and interleukin 6 (IL-6)." (PMID 34206506, 2021). "The macrophage deposition and its chronic activation cause the abnormal secretion of IL-6, TNF-α during SARS-CoV-2 infection in a patient with obesity." (PMID 34220807, 2021).
Obesity (continued). "A previous study reported the association between obesity and elevated circulating levels of pro-inflammatory factors, including cytokines or hormones, such as interleukin-1 and tumor-necrosis-factor." (PMID 34001028, 2021). "Their presence in human adipose tissue has been linked to obesity and insulin resistance, probably due to their interference in PPARγ gene expression, production of inflammatory cytokines, such as tumor necrosis factor-α (TNF-α), and anti-androgenic effect." (PMID 34829943, 2021). "TNFα induced by inflammation during obesity upregulates Sost and contributes to obesity-induced bone loss in mice and in osteocyte cell lines." (PMID 34502021, 2021). "The increase in adiponectin, an inflammatory adipocytokine, such as TNFα, IL-1β, and IL-6, has a large effect on the renal disorders associated with obesity, causing an increase in the mesangial matrix and inflammation of the renal tubular epithelium." (PMID 34959901, 2021). "It is well known, that obesity is associated with increased circulating levels of TNF-α, IL-6, and reactive oxygen species." (PMID 33526854, 2021). "Characterizing the downstream effectors of TNFα signaling in hepatocytes and elucidating subsequent biological implications is fundamental for a systemic understanding of obesity-associated pathologies including the development of T2DM." (PMID 34576943, 2021). "For instance, in elderly mice given systemic anti-tumor immunotherapy, obesity caused a fatal cytokine storm, which increased M1 macrophage polarization, and proinflammatory TNF-α and IL-6 release, leading to a reduced anti-tumor effect and low survival rate." (PMID 34350120, 2021). "Obesity is often associated with an increased risk of systemic inflammation through production of TNF-α and IL-6 from adipocytes." (PMID 34239993, 2021). "Low adiponectin, high leptin, and TNF-α levels were associated with obesity, NASH, and play an important role in CRC-hepatic metastasis." (PMID 34722019, 2021). "Obesity is associated with increased production of pro-inflammatory cytokines, such as IL-6 and TNFα, which are associated with cognitive decline." (PMID 33941254, 2021). "It has been described that proinflammatory cytokines such as tumor necrosis-alpha (TNF-α), interleukin (IL)-1β and IL-6 play a central role in cardiac damage associated with ischemic conditions and obesity, as well." (PMID 34439522, 2021). "Later, tumor necrosis factor-α (TNF-α) was identified as the molecule which mediated obesity-linked IR." (PMID 33511131, 2020). "For example, TNF secretion from adipose tissue and circulating plasma IL-6, both of which play a role in insulin-response, were highly associated with obesity-associated insulin resistance in a human cohort." (PMID 33287442, 2020). "Studies have shown that the upregulation of TNF-α plays an important role in the induction of insulin resistance, which is associated with obesity and DM." (PMID 33603663, 2020). "Obesity-associated insulin resistance is associated with increased levels of pro-inflammatory cytokines, such as TNF-α, IL-1β, and IL-6." (PMID 33260769, 2020). "The pattern of results described in the present meta-analysis and systematic review consistently showed that higher TNF-α levels were associated with pathologically higher BMI scores as a proxy of obesity." (PMID 32545460, 2020). "In patients with COVID-19 and obesity, the IL-6 and TNF-α high serum levels are negatively associated with T-cells." (PMID 33160363, 2020). "Obesity is associated with the state of chronic inflammation and abnormal production of proinflammatory mediators, such as tumor necrosis factor α (TNF-α)." (PMID 32218367, 2020). "Obesity abolished the protective effect of A allele of the TNF-α G-308A polymorphism on DNA damage and on inflammation development observed in non-obese A allele carriers." (PMID 30900134, 2020).
Obesity (continued). "Psoriasis and obesity share common pathogenic mechanisms, i.e., increased production of pro-inflammatory cytokines (IL-1, IL-6, TNF-α, and adiponectin) which are responsible for a chronic low-grade inflammation which are observed in both conditions." (PMID 33187195, 2020). "Obesity-associated inflammation is characterized by elevated serum levels of pro-inflammatory cytokines such as interleukin-1 (IL-1), IL-6, and tumor necrosis factor alpha (TNF-α), as well as altered levels of adipokines such as leptin and adiponectin." (PMID 32295649, 2020). "Specifically, proinflammatory factors such as HMGB1, TNF-α, and IL-1β play critical roles in the inflammation underlying both obesity and preeclampsia." (PMID 32471078, 2020). "Excessive fat, or obesity, is associated with a decrease in adiponectin and/or an increase in leptin, resistin, and tumor necrosis factor-alpha." (PMID 32498328, 2020). "Several inflammatory cytokines, such as IL-1, IL-6, NF-κB, and TNF-alpha, also have been linked to obesity." (PMID 31936158, 2020). "Altogether, these results highlight the association of PVAT-derived TNFα to vascular damage in the context of human obesity." (PMID 33020373, 2020). "Increased adipose tissue TNF-α expression in obesity was reported to be associated with insulin resistance, as well as with weight loss and lipoprotein lipase levels." (PMID 32188105, 2020). "Taken together, this study provides a novel model for the pathologic role of stearic acid to produce MIP-1α/CCL3 in the presence of TNF-α associated with obesity settings." (PMID 33050324, 2020). "Obesity-associated insulin resistance induces abnormal production of inflammatory cytokines such as tumor necrosis factor (TNF)-α and interleukin 6 (IL-6)." (PMID 31991602, 2020). "Studies on animals devoid of the TNF-α encoding gene with diet-induced obesity have shown significant improvement in insulin sensitivity." (PMID 33322719, 2020). "Another meta-analysis reviewing the association between obesity-related adipocytes and breast cancer among Asian women found that increased levels of TNFα was associated with increased risk of postmenopausal breast cancer." (PMID 33004039, 2020). "Participants with higher TNF-α levels were at increased risk of having obesity (OR = 2.34; 95% CI 1.31–4.18)." (PMID 33299020, 2020). "Obesity and its related metabolic abnormalities are associated with increased oxidative stress radicals with elevated expression of NEFAs, TNFa, CRP, IL-6, TNF-α, and LDL cholesterol." (PMID 32069832, 2020). "In this regard, a typical M1-type proinflammatory macrophage polarization was observed in the adipose tissue in obesity and/or T2D which was found to be associated with hyperglycemia, hyperinsulinemia, increased TNF-α expression and adipose tissue hypoxia." (PMID 32188105, 2020). "In contrast, PGE2 production or signaling inhibition has also been shown to be protective against obesity-associated inflammation, as it decreased TNFα, MCP-1 and IL-6 expression by macrophages and AT lipolysis in HFD-fed rodent models and human AT." (PMID 32752107, 2020). "Given that above all childhood overweight and childhood obesity is increasing worldwide and is a major concern of public health, the association between overweight/obesity, TNF-α levels and OSAS demand particular attention." (PMID 32545460, 2020). "We also measured serum concentrations of TNF-α and IL-1β as obesity is highly associated with systemic inflammation." (PMID 33408699, 2020). "The increased TNF-α level is related to the combined effect of obesity and diabetes while increased leptin level is caused by obesity unescorted by diabetes." (PMID 32089876, 2020). "Obesity is also linked to a condition of chronic inflammation, mediated in particular by the cytokines IL-6 and TNF-α, expressed in adipose tissue." (PMID 33167396, 2020).
Obesity (continued). "In contrast, very few monocytes isolated at the end of the CR period expressed TNFα following LPS stimulation, suggesting that fasting supported the loss of obesity-induced pro-inflammatory phenotype in circulating monocytes." (PMID 32085416, 2020). "The excessive consumption of a high-fat diet (HFD), a main environmental factor for obesity, causes abnormal fat accumulation in adipose tissue and the liver, which secretes inflammatory adipokines such as tumor necrosis factor (TNF)-α [1, -3]." (PMID 31986244, 2020). "TLR expression exhibits circadian dynamics that are dependent, in part, on gut microbes and their activation can result in downstream induction of pro-inflammatory cytokines, including TNF-α, IL-6, and IL-1β, driving obesity-associated inflammation." (PMID 33255707, 2020). "Over-expression of Interleukin 6 (IL-6) and tumor necrosis factor-alpha (TNF-α) that regulate the production of high sensitivity C-reactive protein (hsCRP) are linked to hypertension and obesity." (PMID 33171852, 2020). "Secretion of proinflammatory cytokines such as interleukin-6 and tumor necrosis factor-α from obesity-induced hypertrophic fat cells causes muscle atrophy." (PMID 33379405, 2020). "These macrophage populations express high levels of pro-inflammatory cytokines such as IL1β and TNF, and previous studies have shown that deficiency in TNF as well as TNF neutralization can improve glucose and insulin tolerance in mouse models of obesity." (PMID 33330676, 2020). "TNFα plays an essential role in chronic inflammation associated with different pathologies, such as obesity, T2D, AD, and PD." (PMID 32982666, 2020). "Obesity is associated with elevated circulating levels of IL-6 and TNFα, which are subsequently decreased with weight loss." (PMID 32158768, 2020). "Other obesity‐associated factors, such as myostatin, inflammatory cytokines including TNFα and IL‐1β, free fatty acids, and leptin, are suggested to be involved in the regulation of SC proliferation and differentiation post muscle injury." (PMID 32776502, 2020). "Subclinical inflammation in obesity has been associated with early insulin resistance brought upon by leptin-driven and increased levels of TNF-α and subsequent decrease in insulin receptor substrate 1 (IRS-1) signaling and tyrosine kinase activity." (PMID 32295104, 2020). "This obesity-associated inflammation is characterized by increased circulating inflammatory cytokines such as tumor necrosis factor (TNF)and interleukin 6 (IL-6) as well as an increase in pro-inflammatory immune cells, particularly macrophages and lymphocytes." (PMID 33584724, 2020). "There are inflammatory mediators associated with obesity and T2D, such as inteleukin-6 (IL-6), IL-32, tumor necrosis factor – α (TNF-α), that have a direct effect on vascular wall and plaque formation, but they are not within the scope of this work." (PMID 32337369, 2020). "Leptin, adiponectin, IL-6 and TNF-α mainly act in adipocyte metabolism, insulin sensitivity and metabolic disorders associated with obesity." (PMID 33160363, 2020). "TNF-α, which was initially considered a factor involved in necrosis of tumour cells has now been implicated in the cause of insulin resistance and obesity." (PMID 32153977, 2020). "In a rodent model of insulin resistance caused by obesity, the genetic ablation of TNFα, or its receptor, improved insulin sensitivity." (PMID 32575419, 2020). "Obesity is also marked with high concentrations of leptin, which is also known to trigger the production of IL-6 and TNF-α from adipose tissues and to increase the risk for viral infection." (PMID 32650509, 2020). "Obesity is associated with chronic adipose tissue inflammation, which is characterized by elevation of inflammatory cytokines, such as IL-18, TNF-α, and other adipokines released from adipose tissues." (PMID 32917958, 2020).
Obesity (continued). "Both inflammatory markers (CRP, TNF-α) were positively associated with waist circumference (obesity indicator) in the study subjects." (PMID 32670417, 2020). "Obesity is associated with elevated levels of TNF-α and proinflammatory CD11c monocytes/macrophages." (PMID 33033337, 2020). "The concentration of adipokines, such as TNF-α, IL-6 and leptin, were significantly higher in obese subjects and the elevated levels was linked to obesity, and even positively correlated with body mass index." (PMID 32819324, 2020). "Plasma TNF-α levels were found to be associated with visceral fat mass and body mass index (BMI) in patients with obesity/T2D." (PMID 32188105, 2020). "TNFα signaling was one of top upstream transcriptional regulators in the liver of HFD mice, implying that IFNγ- and TNF-mediated inflammatory responses are major events in obesity-associated chronic inflammation." (PMID 33379198, 2020). "On the other hand, obesity is associated with low-grade chronic inflammation, where the enlargement of adipocytes induces the secretion of TNFα and Il6, leading not only to insulin resistance but also to bone loss." (PMID 32664580, 2020). "TNF-α expression in adipose tissues is positively correlated with the degree of obesity and associated type 2 diabetes mellitus(T2DM)." (PMID 32486076, 2020). "IL‐6 and TNF‐α are two typical pro‐inflammatory factors that are implicated in the pathogenesis of obesity‐induced insulin resistance." (PMID 31102492, 2020). "In BAT, macrophage infiltration contributes to the high levels of inflammatory cytokines (TNF, IL-6, and IL-1β) in conditions associated with AT hypertrophy such as high fat diet or obesity." (PMID 32934774, 2020). "Cytokines, interleukin 6 (IL-6) and tumor necrosis factor alpha (TNF-α), which regulate the production of high-sensitivity C-reactive protein (hsCRP) correspondingly are linked to high blood pressure and obesity." (PMID 31671730, 2019). "Obesity is associated with inflammation due to the activation of pro-inflammatory signaling pathways, and expression of tumor-necrosis factor (TNF-alpha) in adipose tissue." (PMID 30856212, 2019). "There is one prior study which has prospectively studied the effects of weight loss in patients with PsA and obesity or overweight starting treatment with a TNF-inhibitor." (PMID 30635024, 2019). "Then, using the db/db mice, an animal model of type 2 diabetes with insulin resistance linked to obesity, we found that both Ca2+ and TNFα signaling underwent distinct alterations in male compared to female." (PMID 30792662, 2019). "Obesity is associated with inflammation and inflammatory cytokines including TNF-α, IL-6 and resistin promote phosphorylation of insulin receptor substrates 1 (IRS-1) at serine sites that negatively regulates normal insulin signaling." (PMID 31226166, 2019). "Leptin, which is augmented in obesity, also up-regulates pro-inflammatory cytokines, such as TNF-α and IL-6, which are associated with insulin resistance and the development of type II diabetes." (PMID 31357412, 2019). "The adipokines leptin, resistin, and TNF-α are also involved in lipid and glucose metabolisms, and their enhanced expressions have been linked with the development of diabetes and obesity." (PMID 30863274, 2019). "Here, we found a gender-specific alteration of Ca2+ and TNFα signaling in db/db mice, a common model of type 2 diabetes linked to obesity." (PMID 30792662, 2019). "Due to possible interference from TNF-α with respect to insulin signaling, TNF-α is considered a causative agent in the pathogenesis of obesity-associated insulin resistance and T2DM." (PMID 31073335, 2019). "M1 macrophages, the CD68 staining immune cells that secrete inflammatory cytokines—TNF-α, IL-6, and IL-1β–that are implicated in promoting obesity-associated inflammation, are abundant in breast WAT." (PMID 31555578, 2019).